BCR (BCR activator of RhoGEF and GTPase)
Diseases named in the same sentence as BCR in open-access papers (continued):
Sharing a sentence is not in itself a finding about the gene and the disease.
cancer (continued). "As apoptosis could not account for the significant reduction in cell number in T315I-mutant or wild-type BCR-ABL cell lines, we predicted that other processes were responsible for reduced cancer cell proliferation in response to AKI603 treatment." (PMID 27824120, 2016). "Finally, transposon insertions are unable to recapitulate reciprocal translocations such as BCR–ABL and other genomic alterations that commonly occur in cancer." (PMID 26481584, 2015). "The K562 line was chosen as a negative control as it is a cancer cell line dependent on BCR-Abl expression to test if our predictor was, in fact, recognizing non-specific dependence on any activated kinase." (PMID 17096850, 2006). "KEGG analysis results showed that the top 20 upregulated signaling pathways included BCR signaling, TCR signaling, and chemokine signaling, whereas the downregulated signaling pathways included TGFβ signaling pathways, pathways in cancer, and calcium signaling pathways (Supplementary S3)." (PMID 39451532, 2024). "At the same time, targeted treatments have been developed which directly stop BCR::ABL1 from affecting cell growth and survival, replacing traditional, more toxic chemotherapy drugs which have a blanket effect on all developing cells, both healthy and cancer cells." (PMID 38550948, 2023). "As the innate BCR/TCR barcode guarantees sufficient complexity for clonal cell tracking, biological systems, such as cancer development accompanied by immune responses, may use TCRs/BCRs to trace the immune cells responsible for cancer progression or inhibition." (PMID 38201231, 2023). "This may be attributed to the lack of ensembling for this dataset, or the nature of the BCR-priors set having cases that eventually turn to cancers sooner hence being easier to discriminate." (PMID 38133069, 2023). "Moreover, BCR–ABL tyrosine kinases are generated by the fusion of portions of BCR and ABL genes that initiate ROS development and a genomic instability cycle that can trigger DNA damage, especially DSBs in human carcinoma." (PMID 35719997, 2022). "In our HC-NPs, we combined the specific anticancer activity of IM that binds specifically to the BCR-ABL oncoprotein present only in the CML cells, and the anticancer property of AgNPs, thanks to the production of ROS, in order to improve their efficacy on cancer cells only." (PMID 31510037, 2019). "Both BCR-ABL and BCR-FGFR1 driven hematopoietic malignancies are considered of stem cell origin, and it is speculated that this may be the same for BCR-PDGFRA, BCR-RET and BCR-JAK2 induced cancers as well, however this remains to be investigated." (PMID 31105873, 2019). "In cancers that do not have the BCR–Abl translocation, ABL1 seems to show reduced expression." (PMID 22075945, 2012). "Therefore, expression of the respective target protein in the cancer cell is mandatory and genetic testing of cancer patients is compulsory, e.g., for HER2/neu overexpression for the use of trastuzumab, HER1 for the use of cetuximab or panitumumab or BCR/ABL1/c-kit for the use of imatinib." (PMID 35582146, 2019). "Unlike other recurrent gene fusions, such as EWS-FLI1, BCR-ABL, and EML4-ALK, which are preferentially enriched in specific cancer subtypes, PVT1 gene fusions occurred across cancer types." (PMID 40027648, 2025). "This dynamic, adaptive approach is not standardised in most other cancers save CML where dose and/or type of TKI therapy is adjusted based on results of sequential MRD-testing for BCR::ABL1." (PMID 38637690, 2024). "Unlike ILK, ABL’s role in mitotic “cancer” centrosomes is not well understood and most studies have focused on the ABL fusion gene product (BCR-ABL)." (PMID 37508338, 2023). "Bisindolylmaleimide IX targets the Raf-Erk pathway by directly inhibiting B-Raf, thus inducing greater cell death of BCR-ABL expressing cells, a mechanism that does not exist in other cancer lines tested." (PMID 27564101, 2016).
cancer (continued). "Gleevec has been introduced as anti-cancer drug not only against cancer cells with BCR-ABL translocation, but also in some cancers not having the translocation." (PMID 19116006, 2008).
infection (48 papers, 2013 to 2026). The state of being infected such as from the introduction of a foreign agent such as serum, vaccine, antigenic substance or organism. "A study focused on the breakthrough infection and pan-variant antivirals, and they successfully identified elite neutralizing antibodies (nAbs) repertoire using scRNA/BCR-seq of B cells, which showed strong neutralizing activity targeting numerous variants." (PMID 39334490, 2024). "Moreover, we show that post-infection vaccination against SARS-CoV-2 following a prior infection caused a significant renewal of the BcR IG gene repertoire." (PMID 40489958, 2025). "Differences in the BcR IG profiles post-infection versus post-vaccination allude to distinct trajectories in B cell maturation." (PMID 40489958, 2025). "In this study, we profiled the BcR IG gene repertoire after the initial infection by the SARS-CoV-2 virus as well as following a complete primary series of immunization with 2 vaccine doses." (PMID 40489958, 2025). "Further comparisons of the amino acid substitution profiles in the BcR IG gene repertoires of individuals analyzed both post-infection as well as post-vaccination revealed two different patterns of SHM acquisition." (PMID 40489958, 2025). "We performed single-cell transcriptome coupled with T-cell/B-cell receptor (TCR/BCR) sequencing in 15 peripheral blood mononuclear cell (PBMC) samples from Omicron infection and naïve with booster vaccination." (PMID 39835127, 2024). "In general, when an infection occurs, an 'immunological footprint' in the form of specific BCR and TCR repertoires can be identified." (PMID 38307916, 2024). "Overall, these data suggest that the nature of the immunisation(s) (vaccine and/or live infection) differentially affects the diversity of the BCR repertoire structure." (PMID 39534604, 2024). "Taken together, our results show that BCR V/J is used at similar frequencies in the vaccinees and breakthrough infection groups, showing germline preference." (PMID 39835127, 2024). "As antigens degrade, get consumed, or decline due to infection clearance, antigen clusters formed by synaptic patterning will likely become smaller, thereby exerting a stronger selection pressure for improving BCR affinity." (PMID 39302963, 2024). "To understand the dynamics of the BCR repertoire during immune responses to Omicron breakthrough infection, we reconstructed BCR sequences by scBCR-seq." (PMID 39835127, 2024). "We further introduced an approach for diagnosing infections using RNA-seq with bioinformatic analysis of BCR and TCR repertoires." (PMID 38307916, 2024). "At the single B cell level, our study demonstrated that acute subjects present an unbalanced amount of P. vivax-IgM BCR versus other isotypes, indicating that those cells are probably engaged in the immune response to infection." (PMID 37027391, 2023). "Despite our study and other studies that have provided a relationship between BCR repertoire and disease infection, detailed work on BCR repertoire is needed to reveal its role in disease progression in asymptomatic patients." (PMID 34531370, 2021). "The results showe that the viability of K562 cells was significantly inhibited by infection with the BCR-ABL sgRNA_2 virus (p < 0.001) compared to infection with the BCR-ABL sgRNA_1 virus (p = 0.011) and scramble virus." (PMID 32485885, 2020). "Interestingly, post-infection SARS-homologous clonotypes utilizing the IGHV3-30 gene acquired SHMs with a predicted major influence on critical BcR IG domains, anticipated to impact the final IG conformation and antigen recognition." (PMID 40489958, 2025). "Pairwise comparisons of the post-infection versus post-vaccination BcR IG gene repertoires in 25 individuals with available longitudinal samples revealed similar repertoire diversity at the two time points (median Shannon index: 5.86 post-infection versus 5.68 post-vaccination)." (PMID 40489958, 2025).
infection (continued). "Lack of BCR diversity on the surface of B-1 cells and reconstitution of IgM-BCR complexes may explain the antigen-specific responses of self-reactive B-1 cells in response to infection by various pathogens, including bacteria, viruses, fungi and parasites." (PMID 38333214, 2024). "BCR-seq is a powerful method that has enabled the in-depth analysis of genetic features of antibody responses and tracking of antibody evolution during an infection/vaccination." (PMID 38433846, 2024). "Following UPEC challenge, the extravascular BCR diversity and unique clonotypes number became more similar to the intravascular compartment, suggesting that infection promotes the entry of intravascular (mostly naïve) B cells with new BCR specificities to the kidney." (PMID 37925420, 2023). "In addition, expression of pro‐inflammatory cytokines including IL‐6 and TNF was slightly downregulated upon infection while BCR‐signalling genes were significantly upregulated." (PMID 34169553, 2022). "Alternatively, these cells may migrate into the mucosa tissue and reside in situ awaiting cognate BCR stimulation upon subsequent infection." (PMID 34351920, 2021). "Higher levels of BCR clonal expansion and B-cell activation are present in the SP group, indicating a more robust humoral immune response happened in severe infection." (PMID 32796814, 2020). "In this context, it is conceivable that expression of IgD BCR is an important element for the execution of a rapid and efficient humoral immune response that provides an evolutionary advantage for the control of an acute infection." (PMID 31015337, 2019). "On the other hand, the function of secondary GCs is to further mature the BCR and generate high affinity plasma cells, a process that may be too slow to prevent overwhelming infection." (PMID 30135429, 2018). "In addition to immune cell composition, analyzing immune cell receptors of B and T cells by employing tools such as MiXCR38 and TRUST439 in combination with BCR/TCR databases can provide a rapid determination of the type of a previously discovered virus or infection." (PMID 38307916, 2024). "Moreover, dysregulated BCR signaling may represent a common mechanism by which GHVs and other pathogens promote regulatory PC generation as an immune evasion tactic during infection." (PMID 28767707, 2017). "Moreover, the application of TCR and BCR sequencing (TCR/BCR‐seq) has further provided insights into the clonal diversity and antigen specificity of T and B cells and how the immune system is mobilized against the virus and how it evolves during the course of infection." (PMID 40183283, 2025). "Significantly downregulated of key components of TCR and BCR signaling pathways, such as ZAP70, BTK, and CD79A, suggested a temporary inhibition of these pathways critical for cellular immunity post-infection." (PMID 39650642, 2024). "Upon infection with the ABL sgRNA_2 virus, the BCR-ABL oncoprotein levels were significantly decreased, compared to those in the ABL sgRNA_2 virus- and scramble virus-infected cells." (PMID 32485885, 2020). "As there is a general understanding that immune responses will result in selection of mutated variants we examined the immune status of the infected fry at time of infection (0.15 g size) by analyzing the mRNA expression of RAG-1, T cell receptor (TCR) and IgM (BCR) by real-time PCR." (PMID 23431359, 2013). "These cells, possibly activated by innate rather than BCR signaling, may have detrimental effects by producing potential autoreactive antibodies to contribute to chronic diseases after infection." (PMID 41446064, 2025). "In addition, the expression of miR-200b and miR-429 is downregulated upon infection of primary B cells, while upregulated in plasma cell lines and upon BCR activation, both of which promote EBV reactivation, suggesting a role for these miRNAs in inducing lytic infection." (PMID 40674434, 2025).
infection (continued). "However, B-cell ontology is not complete in these mice, with little germinal center reactions or BCR maturation, impeding the study of latency II and I. Moreover, lytic infection cannot take place because of the absence of human epithelial cells." (PMID 30662441, 2018). "Definitive experiments would involve murine infection followed by simultaneous sampling of all lymph nodes within BcR transgenic mice to account for migration to non-draining lymph nodes, nasal mucosa and other mucosa-associated lymphoid tissues, as well as skin and liver." (PMID 25171166, 2014).
hematological malignancies (28 papers, 2013 to 2025). "Chronic myeloid leukemia (CML) is a blood disorder caused by a genetic alteration that creates the BCR-ABL fusion gene, leading to continuous activation of cell growth signals and uncontrolled proliferation of the blood cells." (PMID 41008552, 2025). "The identified TCR/BCR repertoires and the observed associations from this work provide useful resources and insights into the future development of novel immunotherapies for hematological malignancies." (PMID 31771646, 2019). "Indeed, 64% of breakpoints in chromosomal translocations implicated in hematological malignancies correspond to common fragile sites, and may account for the increased frequency of BCR as a fusion partner in hematopoietic neoplasms." (PMID 31105873, 2019). "Due to the presence of common coding mutations and/or fusions genes (ETV6-RUNX1, E2A-PBX1, BCR-ABL, etc.)within subgroups of patients, it has been reported that hematologic malignancies have more shared neoantigens than most solid tumors." (PMID 41011272, 2025). "Chronic myeloid leukemia (CML) is a severe hematological malignancy characterized by BCR-ABL fusion gene." (PMID 39635534, 2024). "This is supported by the synergism between TKIs and chemotherapy, which have been proven to be successful in the treatment of other hematological malignancies, including B-cell acute lymphoid leukemia with BCR::ABL1 fusion." (PMID 39457651, 2024). "Chronic Myeloid Leukemia (CML) is a hematological disorder characterized by the clonal expansion of a hematopoietic stem cell carrying the Philadelphia chromosome that juxtaposes the BCR and ABL1 genes." (PMID 34276365, 2021). "The PI3K pathway can be activated by several upstream receptors (IGF-R, Flt3, c-Kit, Notch, TCR, BCR) or intracellular proteins (Ras, BCR/ABL) in various hematological diseases." (PMID 23693095, 2013). "Chronic Myeloid Leukemia (CML) is a hematological disorder characterized by the neoplastic transformation of a hematopoietic stem cell carrying the Philadelphia (Ph) chromosome that juxtaposes the breakpoint cluster region (BCR) and the Abelson1 (ABL1) genes." (PMID 35626209, 2022). "Ibrutinib, a BCR-signaling inhibitor which is under clinical trials for several hematologic malignancies could be a potential compound for inhibition of MYC induced proliferation in B-cell malignancies [NCT02303392]." (PMID 34372899, 2021). "In hematological malignancies, MUC1-C has been associated with various pathways related to disease pathogenesis, such as Wnt/β-catenin, fms-like tyrosine kinase 3 (FLT3), breakpoint cluster region protein (BCR)/Tyrosine-protein kinase (ABL), and NF-κB, which are involved in tumorigenesis." (PMID 34207342, 2021). "While Shp2 is essential in driving BCR-ABL mediated leukemogenesis, our results suggest that Shp2 also plays a vital role in BCR-FGFR1 driven hematologic malignancies." (PMID 35574218, 2022). "Since the detection of BCR-ABL, BCR has been identified as a commonly occurring fusion partner in many other hematologic malignancies." (PMID 35574218, 2022). "As a member of the STAT family, STAT5B plays a key regulatory role in the pathogenesis of various disease drivers, including BCR/ABL and NPM-ALK, and expresses at a high level in hematological malignancies." (PMID 34895266, 2021). "MYC regulating factorsinclude BET family, MCL-1, BCR-signaling mediators, HDACs, PI3Kδ, DNA-PK, CDKs, kinases and G-quadraplex (Refer to “The role of MYC in hematopoiesis and hematological malignancies" section)." (PMID 34372899, 2021).
hematological cancer (11 papers, 2014 to 2025). "For example, hematological cancers chromosome rearrangements, such as BCR-ABL fusion (the Philadelphia chromosome), cannot be identified in current INCM analysis." (PMID 32101536, 2020). "Of these translocations, BCR has been identified as a common fusion partner in hematopoietic cancers with over 5 known fusion partners to date." (PMID 31105873, 2019). "Here we present a timely review, which examines the importance of BCR as a translocation partner in hematopoietic cancers." (PMID 31105873, 2019). "Although the breakpoints for BCR fusion proteins in hematologic cancers vary, they all contain the coiled-coil dimerization domain present in BCR, indicating that the dimerization domain is vital for the oncogenic ability of these fusions." (PMID 31105873, 2019). "For instance, bortezomib and ruxolitinib (a JAK1/2 inhibitor targeting STAT3) have shown promise in other hematologic cancers and may enhance therapeutic strategies when combined with BCR inhibitors." (PMID 40129242, 2025). "The identification of oncogenic BCR fusion proteins emphasizes the importance of determining malignant genetic alterations in patients and stresses the need for the development of personalized medical treatments for hematopoietic cancers." (PMID 31105873, 2019). "In addition to these well characterized fusion proteins, other BCR fusions have been discovered in solid tumors and hematological cancers, however these fusions have yet to be studied." (PMID 31105873, 2019). "Furthermore, inhibition of Shp2 maybe beneficial for these BCR-fusion protein driven hematologic cancers, however, this remains to be investigated." (PMID 35574218, 2022). "As mutations in STAT5B, but not STAT5A, have been frequently described in hematopoietic tumors, we used BCR/ABL as model systems to investigate the contribution of STAT5A or STAT5B for leukemogenesis." (PMID 30679796, 2019).
hematologic neoplasm (5 papers, 2021 to 2023). "Chronic myeloid leukemia (CML) is a hematologic neoplasm characterized by the expression of the BCR::ABL1 oncoprotein, a constitutively active tyrosine kinase, resulting in uncontrolled growth and proliferation of cells in the myeloid lineage." (PMID 38004514, 2023). "Further, it was demonstrated that PTPN11 is necessary for BCR::ABL1-induced hematologic neoplasms, as its deletion compromised induction of CML in mice." (PMID 37384296, 2023). "CML is a hematologic neoplasm sustained by the constitutive activation of the BCR::ABL1 fusion kinase that can successfully be targeted with TKIs, so that most CML patients nowadays obtain durable remissions." (PMID 35992847, 2022). "Agents worth testing in combination studies include FLT3 inhibitors in AML, BCR signaling inhibitors in certain NHL subtypes, and BH3 mimetic drugs (BCL2 inhibitor venetoclax and MCL-1 inhibitors) in a variety of blood cancers." (PMID 34408976, 2021). "We examined the convergence on de novo lipid synthesis in RAS, BCR-ABL, and MYC-driven hematopoietic tumor cells." (PMID 34399819, 2021).
infectious disease (2 papers, 2020 to 2021). A disorder directly resulting from the presence and activity of a microbial, viral, or parasitic agent in humans. "TCR and BCR repertoire profiling are important to reflect the disease’s adaptive immune status and develop new therapeutics for infectious disease." (PMID 34531370, 2021). "We have extended the approach to characterize serum Ab responses to vaccines by alignment of peptides to antigen-specific single BCR, and this can also be used to analyze circulating Abs involved in autoimmune or infectious diseases." (PMID 33048842, 2020).